CDC14C (cell division cycle 14C)
Description:
Dual-specificity phosphatase. Preferentially dephosphorylates proteins modified by proline-directed kinases (By similarity).
Synonyms: CDC14B2; CDC14Bretro; MGC26484; CDC14CP
Tractability: Antibody: UniProt predicts a signal peptide or a membrane-spanning region.
Gene: Protein-coding gene on chromosome 7 (48,924,547 to 48,927,454, forward strand). Ensembl gene ENSG00000218305.
Subcellular location: Endoplasmic reticulum membrane
Gene Ontology:
Molecular function: protein serine/threonine phosphatase activity; protein tyrosine phosphatase activity
Biological process: cilium assembly; microtubule cytoskeleton organization; positive regulation of cytokinesis; regulation of exit from mitosis
Cellular component: endoplasmic reticulum membrane; cytoplasm; mitotic spindle; nucleolus; spindle pole
Genetic constraint (gnomAD): Loss-of-function variants: 4 observed, 6.28 expected, observed/expected ratio (o/e) 0.64, 90% interval 0.31 to 1.43. That is too few expected variants to judge how well the gene tolerates losing a copy. Missense variants: 113 observed, 125.03 expected, observed/expected ratio (o/e) 0.9, 90% interval 0.77 to 1.06. Synonymous variants: 54 observed, 40.85 expected, observed/expected ratio (o/e) 1.32, 90% interval 1.06 to 1.66.
Homologues: Orthologues: macaque CDC14C (88% identical), dog CDC14B (84% identical), rat Cdc14b (82% identical), guinea pig Cdc14b (81% identical), mouse Cdc14b (80% identical), tropical clawed frog cdc14b (58% identical), zebrafish cdc14b (52% identical). Paralogues in human: CDC14B (90% identical), CDC14A (56% identical), PTPDC1 (17% identical), PALD1 (14% identical), PTP4A1 (11% identical), PTP4A2 (11% identical), PTP4A3 (10% identical), CDKN3 (9% identical).
Diseases named in the same sentence as CDC14C in open-access papers:
CDC14C is named in the same sentence as 1 disease in open-access papers, as found by Europe PMC text mining. Sharing a sentence is not in itself a finding about the gene and the disease.
CDC14C shares sentences with these, for which no sentence is quoted: lung adenocarcinoma (1 paper).